CDK12 (cyclin dependent kinase 12)
Diseases named in the same sentence as CDK12 in open-access papers (continued):
Sharing a sentence is not in itself a finding about the gene and the disease.
embryonic carcinoma (1 paper, 2019). "When neuronal differentiation model of mouse embryonic carcinoma cell (P19) was employed, CDK12 and CDK13 kinases participated in the axonal elongation through a common signaling pathway that modulates protein expression of CDK5." (PMID 31440507, 2019).
female infertility (1 paper, 2025). Diminished or absent ability of a female to achieve conception. "In summary, the absence of CDK12 in the oocyte leads to an interruption of oocyte development to fully grown GV stage and thus to a termination of folliculogenesis, resulting in female infertility." (PMID 40148269, 2025). "In conclusion, the results show that the absence of maternal CDK12 in oocytes leads to female sterility." (PMID 40148269, 2025). "Taken together, our results clearly demonstrate that the absence of CDK12 leads to an abnormal transcriptome and translatome of the growing oocyte, which in turn results in the absence of a fully mature oocyte and leads to female infertility." (PMID 40148269, 2025). "Next, we investigated why absence of CDK12 in oocytes leads to female infertility." (PMID 40148269, 2025).
myeloma (1 paper, 2022). "Our findings suggest that using a CDK12 inhibitor in combination with other DNA repair inhibitors may establish an effective therapeutic regimen to benefit myeloma patients." (PMID 35163134, 2022).
myeloproliferative neoplasm (1 paper, 2026). A clonal hematopoietic stem cell disorder, characterized by proliferation in the bone marrow of one or more of the myeloid (i.e., granulocytic, erythroid, megakaryocytic, and mast cell) lineages. "Elevated CDK13 expression has been reported in myelodysplastic/myeloproliferative neoplasm with ring sideroblasts and thrombocytosis (MDS/MPN-RS-T), in which 80–90% of patients harbor SF3B1 mutations, a splicing factor regulated by CDK12/13." (PMID 41491919, 2026).
myotonic dystrophy (1 paper, 2021). An inherited progressive disorder affecting the muscles. "The main target of one subset of these kinase inhibitors was identified as CDK12, which provides a novel druggable molecular target for myotonic dystrophy." (PMID 34948025, 2021). "Given the significant relationship between CDK12 inhibition and elimination of nuclear foci, refined targeting of CDK12 may help us to develop a potential method to eliminate the RNA pathogenetic mechanisms in myotonic dystrophy." (PMID 34948025, 2021).
osteoporosis (1 paper, 2025). A condition of reduced bone mass, with decreased cortical thickness and a decrease in the number and size of the trabeculae of cancellous bone (but normal chemical composition), resulting in increased fracture incidence. "CDK12 is a potential target for the treatment and prevention of osteoporosis, and overexpression of CDK12 can inhibit osteoblast differentiation." (PMID 40128652, 2025).
papillary thyroid cancer (1 paper, 2020). "Herein, we performed this study to investigate the function of CDK12 and its underlying mechanism in papillary thyroid cancer progression." (PMID 32489449, 2020). "Western blotting further confirmed the mechanism of CDK12 in papillary thyroid cancer through the c-myc/β-catenin pathway." (PMID 32489449, 2020). "CDK12 can affect the c-myc/β-catenin pathway to stimulate papillary thyroid cancer proliferation and metastasis.CDK12 might be a new therapeutic target for papillary thyroid cancer." (PMID 32489449, 2020). "Inhibiting CDK12 might be a new method in papillary thyroid cancer therapy." (PMID 32489449, 2020). "However, the detailed mechanism of CDK12 in papillary thyroid cancer remains largely unknown." (PMID 32489449, 2020). "Hence, CDK12 may play an important role in papillary thyroid cancer progression." (PMID 32489449, 2020). "Additionally, the CDK12 mRNA expression levels of TPC-1 and KAT-5 cells were the highest among the papillary thyroid cancer cell lines." (PMID 32489449, 2020).
penile carcinoma (1 paper, 2022). "According to mycancer genome, CDK12 mutations are discovered in less than 5% of penile carcinoma patients investigated." (PMID 36564761, 2022).
premature ovarian failure (1 paper, 2025). "In addition, we provide insight into the etiology of premature ovarian failure, in which CDK12 may also play an important role in humans, warranting further investigation." (PMID 40148269, 2025). "CDK12 has been also shown to play a role in the PI3K/AKT/mTOR pathway, which is a critical signaling cascade involved in primary ovarian insufficiency (POF)." (PMID 40148269, 2025). "In summary, the absence of CDK12 affects the expression of some selected mRNAs related to translation and the premature ovarian failure phenotype." (PMID 40148269, 2025). "Among the downregulated transcripts and proteins, premature ovarian failure (POF) markers such as Rps26, Figla, Gdf9, Aire and Fmrp1 were detected, so the absence of CDK12 clearly resembles a POF phenotype." (PMID 40148269, 2025).
renal cell carcinoma (1 paper, 2017). "Four genes (BRCA2, CDK12, MLL2, and VHL) were differentially mutated (p-value < 0.05) between renal cell carcinoma patients and sarcoma patients; however, these differences were not significant when correcting for multiple comparisons (FDR q-values >0.5)." (PMID 29383146, 2017).
seminoma (1 paper, 2025). A radiosensitive malignant germ cell tumor found in the testis (especially undescended), and extragonadal sites (anterior mediastinum and pineal gland).
thyroid cancer (1 paper, 2020). "Then, we downregulated CDK12 expression in the thyroid cancer cell lines TPC-1-shCDK12 and KAT-5-shCDK12." (PMID 32489449, 2020).
viral infection (1 paper, 2025). "Although its functions have been extensively studied in cancer (28, –, 32), the role of CDK12 in viral infection has not been previously reported." (PMID 39601580, 2025).
visceral leishmaniasis (1 paper, 2025). A severe form of leishmaniasis characterized by irregular bouts of fever, substantial weight loss, swelling of the spleen and liver, and anemia (which may be serious). "One notable target is cyclin-dependent kinase 12 (CDK12), whose inhibition has demonstrated efficacy against Leishmania parasites, suggesting its potential as a therapeutic target for visceral leishmaniasis." (PMID 40492115, 2025).
tumor (162 papers, 2013 to 2026). "In vivo, CDK12 inhibition decreases tumor burden and improves colitis-associated CRC histopathology." (PMID 41491919, 2026). "CDK12 loss also defines immunogenic tumor subsets characterized by tandem duplications, gene fusions, and increased neoantigen production, predicting responsiveness to immune checkpoint blockade." (PMID 41491919, 2026). "The loss of CDK12 function profoundly impacts tumor immunogenicity through multiple, interconnected mechanisms." (PMID 41491919, 2026). "We go on to show that loss of CDK12 activity enhances ATP production both in cell line models and in patient tumours." (PMID 41896195, 2026). "Persistent replication stress in CDK12-deficient cells contributes to chromosomal instability, a recognized driver of tumor evolution and chemoresistance." (PMID 41491919, 2026). "Patients with CDK12 mutations often exhibit aggressive tumor phenotypes characterized by genomic instability and poor therapeutic outcomes, underscoring the kinase’s importance in maintaining genomic integrity and modulating cellular responses to treatment." (PMID 41395253, 2025). "Here, we employed novel tubo-ovarian HGSC mouse models to show that Cdk12 loss indeed enhances both tumorigenesis and tumor progression." (PMID 40504161, 2025). "Genetic alterations in CDK12 are strongly associated with tumor progression, metastasis, and resistance to therapy, highlighting its critical role in PCa pathogenesis." (PMID 41395253, 2025). "Patients with poorer clinical outcomes were more likely to have mutations in BRCA2, ATM, and CDK12, as well as high tumor mutation burden (TMB) and microsatellite instability (MSI)." (PMID 40805284, 2025). "Loss-of-function mutations in CDK12 occur in 1–7% of various tumour types, with the highest prevalence in metastatic prostate cancer." (PMID 39895499, 2025). "Our findings revealed that Cdk12 loss promotes tumor progression and impairs survival in the m-sgPRN model." (PMID 40504161, 2025). "We therein establish CDK12 as a bona fide tumor suppressor, mechanistically define how CDK12 inactivation causes genomic instability, and advance a therapeutic strategy for CDK12-mutant mCRPC." (PMID 39368479, 2024). "To accurately estimate the association between CDK12 expression and the tumour microenvironment (TME) in a pancancer dataset, we then investigated the relationship between CDK12 expression and a variety of major types of immunomodulators." (PMID 38503865, 2024). "We have found that in most cancers, high CDK12 expression leads to the proliferation of various immune cells, such as tumour-associated macrophages (TAMs), neutrophils, and helper T cells (Th)." (PMID 38503865, 2024). "In PCa, CDK12 inactivation is known to increase the immunogenicity of tumor cells, but the relationship between CDK12 loss and MHC expression has not been investigated." (PMID 38704603, 2024). "In our retrospective study of 53 primary PCa cases from this Institute, we found a 4% (2/53) prevalence of CDK12 mutations, with the confirmation of this defect in one tumor through Sanger sequencing." (PMID 38704603, 2024). "Meanwhile, we also observed that the growth rate of CDK12‐deficient xenograft tumours was slower than that of CDK12 wild‐type xenograft tumours." (PMID 38736108, 2024). "We provide compelling evidence that Cdk12 is a tumor suppressor gene and demonstrate its loss promotes androgen receptor (AR) and MYC-mediated hypertranscription, transcription-replication conflicts (TRCs), and resultant DNA damage." (PMID 39368479, 2024). "Subsequent ROC curves were used to further study the diagnostic accuracy of CDK12 under 1-year, 3-year, and 5-year survival times of various types of tumours." (PMID 38503865, 2024).
tumor (continued). "Genomic alterations of CDK12, which include mutations, deletions, amplifications and rearrangements, were documented in about thirty tumor types with an incidence of up to 15% of cases." (PMID 37811895, 2023). "Earlier studies indicated that ablation of CDK12 function, or introduction of tumor-related mutations, conferred sensitivity to PARPi." (PMID 37202753, 2023). "Only one tumor sample (patient 3) had a high HRD score of 59, likely due to an oncogenic CDK12 mutation (NP_057591.2:p.Arg1067Ter) found in this tumor which is associated with HRD." (PMID 38134458, 2023). "While variant allele frequency of the CDK12‐altered tumors would have been of value to determine its impact on overall tumor biology, this detail was unavailable in the majority of the sequencing assays in our cohort." (PMID 34898046, 2022). "Confirming a link between CDK12-/- and hyper-duplicated (4/5 tumours), we identify an additional association with MYC CN gain." (PMID 36045381, 2022). "Previous studies demonstrated that CDK12/13 inhibition preferentially decreases the expression of key SE‐associated genes and DNA damage response genes in tumour cells." (PMID 36254394, 2022). "In both the HRD-DNA and HRD-RNA models, samples with biallelic loss of CDK12 were enriched for HRD+ predictions across tumor types." (PMID 35643464, 2022). "Here we found the relative frequency of duplications per tumour to be significantly correlated with CDK12 mutation (adjusted p-value = 0.001) with four hyper-duplicated tumours found to be CDK12−/−." (PMID 36045381, 2022). "Cyclin-dependent kinase 12 (CDK12), as a transcription-associated CDK, plays important roles in tumor-promoting behaviors, whereas the underlying mechanisms of CDK12 in CC progression are still obscure." (PMID 33628849, 2021). "CLEC5A expression was significantly associated with TTN and CDK12 mutations and affected the copy number of tumor progression and immune-related genes." (PMID 34712666, 2021). "On this basis, several clinical trials are ongoing to verify the increased sensitivity of tumours harbouring CDK12 mutations to PARPi." (PMID 34092037, 2021). "The tumour-suppressive role of CDK12 is linked to its ability to maintain genome stability via regulating the transcription of DNA repair genes." (PMID 34316683, 2020). "As the biallelic loss of CDK12 is common in other types of tumours and in some of them is associated with focal tandem duplications, the CDK12 aberrations have a potential to be used, next to MMR deficiency, as another biomarker of response to the therapy." (PMID 34316683, 2020). "The inactivation of CDK12 (mutations and deletions in the kinase domain) results in the loss of catalytic activity and tumour-suppressive function of the kinase." (PMID 34316683, 2020). "Using capture sequencing, we found CDK12 mutations in 5/124 tumor samples (4% mutation frequency) which is comparable to that originally reported by the TCGA in 2011 (9/316, 3%) and recently reported by Berger and colleagues (21/523, 4%)." (PMID 32639993, 2020). "CDK12 aberrations in tumours include mutations, deletions, amplifications, rearrangements and overexpression." (PMID 34316683, 2020). "Another small cluster of mainly HGSC tumours (11, n = 6), was associated with higher probability of the L-Dup signature, and CDK12 mutations, an association supported by a previous study." (PMID 30794536, 2019). "We found that high levels of CDK12 were associated with worse OS in patients with a residual tumor after surgery < 2 cm." (PMID 29872499, 2018). "This suggestion can be further supported by the fact that more of the key DDR proteins were observed to be deregulated in patient tumor samples bearing CDK12 mutations." (PMID 29090014, 2017). "While CDK12 typically functions as a tumor suppressor, its loss drives context-dependent outcomes." (PMID 41491919, 2026).
tumor (continued). "Integrating inflammatory biomarkers with PSA or mpMRI may enhance diagnostic accuracy and guide personalized immunotherapeutic strategies, such as targeting NF-κB or tumor-associated macrophages via CDK12/13 inhibition or CD47 blockade." (PMID 41293737, 2025). "In solid cancers, CDK12 has been associated with both tumor suppressive and oncogenic functions." (PMID 40389480, 2025). "Tumor sequencing identified a somatic CDK12 pathogenic variant (PV) with loss of heterozygosity." (PMID 41149505, 2025). "We found that inactivation of CDK12 was significantly associated with a tumor-specific enrichment of STING activity signature, along with signatures primarily composed of IFN-stimulated genes that could be induced by STING activation." (PMID 40955658, 2025). "Similarly, detailed understanding of how Cdk12 ablation mitigates tumor progression in the setting of Pten loss—and the degree to which it represents another form of synthetic lethality—is an important future direction." (PMID 39368479, 2024). "Importantly, the sensitivity of ARID1A-deficient tumor cells to SR-4835, a CDK12/CDK13 inhibitor, suggests a promising therapeutic approach for individuals with ARID1A-mutant tumors." (PMID 38835016, 2024). "Therefore, the ETC inhibitor IACS‐010759 can effectively inhibit the growth of CRPC tumours in vivo, and it is more effective for CDK12‐deficient CRPC tumours." (PMID 38736108, 2024). "Notably, the increase in the E4/E6 mRNA ratio in tumor versus normal tissue was also associated with increased CDK12 mRNA expression." (PMID 38132164, 2023). "CDK12 mutations and amplifications have been reported in different tumor types." (PMID 35912188, 2022). "Tumor mutational burden (TMB) was evaluated in tumors with CDK12 alterations." (PMID 34898046, 2022). "Similarly, the highest scoring target mRNA identified for sdRNA-A24 is CDK12, a known tumor suppressor mutated in ~6% of patients with metastatic castration-resistant PCa (bottom)." (PMID 35455981, 2022). "Notably, inactivation of CDK12 is associated with a distinct phenotype of the tumour, characterised by elevated genomic instability, tandem duplications and possible immunogenicity." (PMID 34092037, 2021). "Additional genomic predictive biomarkers for response to immunotherapy have also recently been identified; mutations within cyclin-dependent kinase 12 (CDK12), a tumour suppressor protein with roles connected to genomic stability, have also been demonstrated to lead to the creation of neoantigens." (PMID 34357131, 2021). "We next investigated the underlying mechanism of CDK12-induced tumor progression." (PMID 32483448, 2020). "As above discussed, ~5% of mCRPC patients harbor genetic alterations of CDK12 and these tumors are associated with a high tumor neoantigen burden, which might increase the probability of response to immunechekpoint inhibition." (PMID 31366128, 2019). "Several trials with immune checkpoint inhibitors as a single agent treatment or as combination therapy are currently ongoing in both unselected as in immunogenic subtypes, such as those harboring microsatellite instability, high tumor mutational load or biallelic inactivation of CDK12 or BRCA2." (PMID 31727154, 2019). "Among the other phosphorylation events that depend on CDK12 activity are several that affect proteins involved in mitosis, and we surmise that defective phosphorylation of these proteins in CDK12-deficient ovarian and prostate cells contributes to tumor development." (PMID 31652541, 2019). "A growing number of studies describe mutations or amplification of the CDK12 gene in tumor samples." (PMID 29090014, 2017). "CDK12 loss in a tumor could serve as another marker for treatment with PARP1/2 inhibitors or additional inhibitors of DDR network, as well as with other DNA-damaging compounds." (PMID 29090014, 2017).